PARP1 (poly(ADP-ribose) polymerase 1)
Diseases named in the same sentence as PARP1 in open-access papers (continued):
Sharing a sentence is not in itself a finding about the gene and the disease.
tumor (continued). "Knockout and transgenic models for PARP-1, PARP-2, and PARG have deepened understanding of PARylation’s role in tumour biology." (PMID 41294806, 2025). "Inhibition with TG101209 and AZ960 reduces proliferation in tumorigenic SP/CD44+ cells, while momelotinib suppresses tumor growth by targeting JAK2 and downregulating PARP1 through the IFNGR-JAK2-STAT1-PARP1 axis." (PMID 41438763, 2025). "The A. absinthium leaf and A. annua leaf extracts exhibited cytotoxicity against the tumor cells and they were able to modulate the molecular targets MDR1 and PARP-1." (PMID 40219097, 2025). "In triple‐negative breast cancer (TNBC), ubiquitin‐specific protease 15 (USP15) (a deubiquitinating enzyme) stabilizes PARP1, enhancing BER capacity and promoting tumor cell proliferation." (PMID 40904702, 2025). "AZD5305, a new generation of PARP1 specific inhibitor, is also a PARP1-DNA trapper, which showed good efficacy in vivo using the BRCA mutant HBC-17 patient-derived tumor xenograft (PDX) model." (PMID 37588193, 2024). "The PEGylated form of a PARP1 inhibitor, combined with TMZ, shows significant activity in MRT models, is well tolerated in mice, and results in objective tumor responses in five out of six tested MRT xenografts." (PMID 38893160, 2024). "In conclusion, this work identified the first PARP1/NRP1 dual-targeted inhibitor and provided an effective strategy for constructing dual-targeted drugs for efficient tumor therapy." (PMID 39679370, 2024). "To investigate NK cell-mediated tumor killing and NK cell infiltration in a xenograft mouse model, we performed immunohistochemical analyses using antibodies against cleaved PARP1 and NKG2D in tumor tissues." (PMID 38200153, 2024). "However, PARP-1 seems not to be the cause of carcinogenesis, since it may act as a tumour suppressor, likely due to its role in DNA repair." (PMID 36902215, 2023). "Olaparib, which inhibits PARP-1/2/3, modifies SSB repair and displays significant radiosensitizing effectiveness when administered for treating Lewis lung cancer cells and tumor xenografts." (PMID 37351512, 2023). "In preclinical studies, the combination of pamiparib (PARP1 inhibitor) and TMZ overcame TMZ resistance and showed significant tumor suppression." (PMID 37576862, 2023). "In response to hypoxia, PARP-1 regulates the stability and the activity of both HIF1 and HIF2, promoting tumor cell survival." (PMID 36831435, 2023). "Poly(ADP-ribose) polymerase-1 (PARP-1) is a key enzyme in the DNA repair process, and the overexpression of PARP-1 in several tumours makes this enzyme a promising molecular target." (PMID 36832085, 2023). "Mechanistically, FOXD3-AS1 interacts with poly (ADP-ribose) polymerase 1 (PARP1) in nucleus to prevent poly (ADP-ribosyl)ation and activation of CTCF, resulting in decreasing of downstream tumor-suppressive genes." (PMID 36923440, 2023). "The poly ADP-ribose polymerase 1 (PARP1) inhibitor BYK204165 antagonized the cytotoxic effects of fascaplysin, indicating that DNA repair was involved in its anti-tumor effects." (PMID 37103365, 2023). "PARP1 and PARP2 have distinct roles and mechanisms in tumour development, despite sharing a similar catalytic domain." (PMID 37667522, 2023). "miR-125b-5p acts mainly as a tumour suppressor in many different ways, for example, interacting with VEGF (vascular endothelial factor), PARP 1 (poly-ADP-ribose-polymerase 1) and PRXL2A (peroxiredoxin like 2A gene, responsible for anti-oxidative processes)." (PMID 38139300, 2023).
tumor (continued). "PARP-1 activity in active and inactive cells at 24 and 48 h following irradiation was associated with increased ROS production, and the inhibition of PARP-1-related ROS production may provide an additional opportunity to increase tumor cell sensitivity to other therapeutic agents." (PMID 37351512, 2023). "In CSCs, NAMPT regulates epithelial-mesenchymal transition (EMT) and tumor dedifferentiation/reprograming via controlling cellular functions that promote proliferation and pathways mediated by SIRT1 and PARP1." (PMID 36819783, 2023). "PARP-1, one of the PARP (poly ADP-ribose polymerase) family of enzymes, is overexpressed in tumor cells compared with normal tissue." (PMID 37145164, 2023). "Inhibiting PARP1 to allow expression of NKG2D-L is therefore a promising therapeutic approach targeting therapy-resistant and tumor-forming leukemia stem cells." (PMID 37143070, 2023). "In tumor and adjacent normal tissues, we confirmed that AARS1-overexpressing tumors exhibited K-Ala modification on PARP1." (PMID 36991000, 2023). "Therefore, a consideration of the activation of IKK/NF-κB signaling by genotoxic stress could improve predicting the efficacy of PARP-1 inhibition and expand the application of inhibitors to tumor cells in which IKK/NF-κB activity is upregulated or constitutively active." (PMID 37817938, 2023). "For example, PRRT in combination with a poly(ADP-ribose) polymerase-1 (PARP)-inhibitor, checking the DNA repair mechanism, was shown to prolong tumor growth-inhibition and improve the median survival in a preclinical model compared to PRRT alone." (PMID 37242457, 2023). "Intravenous injection of SKOV3-derived EVs showed significant accumulation in tumor tissues of SKOV3 xenograft mice and resulted in significant PARP-1 knockout, exhibiting 27% indel efficacy." (PMID 36297672, 2022). "Overexpressed PARP-1 enhances tumor angiogenesis by upregulating VEGF, thereby promoting tumor growth and metastasis." (PMID 35906622, 2022). "Treatment with FOXD3‐AS1 constructs or siRNA targeting PARP1 or CTCF reduces tumor growth and prolongs survival in tumor‐bearing nude mice xenografts." (PMID 35592755, 2022). "The dissected tumor tissue were sectioned and evaluated for [225Ac]-PSMA-617 signal by autoradiography in the treatment group and both groups were immunostained for PARP-1." (PMID 35906379, 2022). "In tumour cells, TRAIL stimulates PARP-1 activation and subsequently the PARylation of high-mobility group box protein 1 (HMGB1) which results in HMGB1 localisation to the cytoplasm." (PMID 36159999, 2022). "Over 9 years during which the patient received multiple lines of therapy, the tumor maintained BRCA1 LOH, copy number gains in ABCB10/11, high aneuploidy scores (≥13), MYC amplifications (CN ≥ 10) and PARP1 gains (CN = 4)." (PMID 36344544, 2022). "PARP inhibitor (PARPi) inhibits the recruitment of DNA repair protein by capturing PARP1 and PARP2 on DNA damage sites, blocking the mitotic catastrophe of tumor cells." (PMID 36520958, 2022). "Olaparib is a PARP1 inhibitor that blocks polyADP-ribosylation, which is involved in the epithelial–mesenchymal transition (EMT) characteristic of tumor recurrence." (PMID 35269669, 2022). "Treatment with PARPi suppressed the PARP-1/HMGB1 pathway and re-sensitized tumour cells to TRAIL induced cell death suggesting PARPi can sensitize tumours to NK-cell mediated apoptosis." (PMID 36159999, 2022). "The protein expression level of PARP1 and PAR was measured by Western blot in cell lines and by immunohistochemistry in PDX tumor tissues." (PMID 35419627, 2022).
tumor (continued). "The data demonstrated that TAX promoted the expression of the pro-apoptotic gene Bax, Caspase-3, and Caspase-9, and inhibited the expression of the anti-apoptotic gene Bcl-2 and oncogene Poly ADP ribose polymerase (PARP1) in SPC-A1 and LLC tumor cells." (PMID 36230568, 2022). "Surprisingly, our results from multiplex immunofluorescence assay showed that high expression of PARP1 in stroma cells significantly prolonged PFS and OS in patients with EOC, which was inversed in tumor cells." (PMID 35875162, 2022). "Tumor-secreted lactate downregulates p62 in the stroma by reducing NAD+, which impairs PARP-1 activity, blocking AP-1-mediated p62 transcription." (PMID 35545049, 2022). "Previous work shows that recently, the combined inhibition of PARP1 and DNA‐PK was found to suppress HNSCC tumor growth in vitro and in vivo compared to either agent used alone." (PMID 34977872, 2021). "In conclusion, our work sheds light on the tumor suppressive effect of PLA2R1 during aging and its downstream effectors: ROS, PARP1, and DNA damage and its downstream tumor suppressive pathway." (PMID 33594040, 2021). "Inhibition or knockout of PARP-1 on an inactive PRC2 background leads to NF-κB activation, increased angiogenesis, and macrophage polarization to the tumor-promoting M2 phenotype." (PMID 33923319, 2021). "Mechanistically, FOXD3-AS1 interacts with poly (ADP-ribose) polymerase 1 (PARP1) to repress the poly(ADP-ribosyl)ation and activation of CCCTC-binding factor (CTCF), leading to de-repression of downstream tumour-suppressive genes." (PMID 33671241, 2021). "The combined use of PARP1 inhibitors with OXA can significantly inhibit activity of GC organoids, which affects their tumor initiation ability." (PMID 34497808, 2021). "The pro-apoptotic tumor suppressor BIN1 inhibits the activities of the neoplastic transcription factor MYC, poly (ADP-ribose) polymerase-1 (PARP1), and ATM Ser/Thr kinase (ATM) by separate mechanisms." (PMID 34948122, 2021). "Poly(ADP-ribose) polymerase 1 co-localizes with MIF to the DNA replication fork, where MIF nuclease activity is required to resolve replication stress and facilitates tumor growth." (PMID 34012010, 2021). "Overall, the presence of PARP-1 and PARP-2 in the tumor microenvironment appears to limit anticancer immunity and support tumor growth." (PMID 33923319, 2021). "Inhibition of either PARP1 or SIRT1 alone or in combination with chemotherapy has an advantage in eliminating tumors or inhibiting tumor invasion." (PMID 34445574, 2021). "These defects can be used to target tumours using PARPi, that bind to the NAD+ binding domain of several PARPs, predominantly PARP1/2, inhibiting their catalytic activity and trapping them on DNA." (PMID 35096828, 2021). "Meanwhile, we performed a relationship analysis of PARP1 expression with TMB, MSI, and tumor immune infiltrations as well, based on the online database." (PMID 34531868, 2021). "Topoisomerase-1 (Top1) inhibitors result in formation of SSBs, which require PARP1-mediated SSB repair to prevent DSB formation and tumour cell death." (PMID 34440228, 2021). "PARP1 physically interacts with HIF-1α and HIF2 and protects them from von Hippel–Lindau tumor suppressor-mediated ubiquitylation and degradation." (PMID 33922595, 2021). "They exploit this genetic liability for therapeutic purposes using a combination of fluorinated deoxyuridine analogues and PARP1 inhibitors to target the BER pathway, inducing cytotoxicity and suppressing tumor growth in mice." (PMID 34253820, 2021). "She initially received 6 weeks of radiotherapy and veliparib (PARP1/2 inhibitor), followed over several months by 8 carboplatin and HDAC inhibitor infusions by convection enhanced delivery with significant tumor regression." (PMID 32680567, 2020).
tumor (continued). "It has been demonstrated that nuclear cGAS is recruited to double-stranded breaks and interacts with PARP1 via poly(ADP-ribose), leading to suppression of homologous recombination and thereby promotion of tumor growth." (PMID 32474700, 2020). "A significant decline was observed in PARP-1 and PARP-2 protein expression levels in tumors of both LC and LC-COPD patients compared to the respective non-tumor samples in both groups." (PMID 33187221, 2020). "Targeting of the MYC paralog-PARP1-DDR signaling pathway using the combination of BETi JQ1 and PARPi BMN673 demonstrated excellent anti-tumor efficacy in MYC paralog-dependent SCLC cells." (PMID 33134168, 2020). "While both PARP1, XRCC4 and ERCC1 are related to tumor resistance and metastasis, the specific biological mechanism and the existence of a common mechanism of action between the three are unclear and need further study." (PMID 33184404, 2020). "As expected, levels of the full-length protein were higher in tumor extracts of control animals receiving PBS, while increased cleavage of PARP1 was observed in tumors of treated mice." (PMID 32033490, 2020). "In contrast, approximately 67.67% of the tumor samples with high TLR9 expression showed weak PARP1 staining or no staining, and 77.77% of those with low TLR9 expression showed strong PARP1 staining (p < 0.001)." (PMID 32483468, 2020). "Munoz-Gamez, J. A. etc. found that PARP1 regulated autophagy by the ATP- and NAD + -mediated AMPK-mTOR pathway in human tumor cells." (PMID 33262410, 2020). "Our study is the first study to show that haplotypes comprising of 5 SNPs on PARP1 (rs1136410, rs3219073, rs1805414, rs1805404, rs1805415) is able to differentiate the NSCLC tumor from normal tissues." (PMID 33284833, 2020). "Poly (ADP-ribose) polymerase 1 (PARP-1) is an ADP-ribosylation enzyme that is essential for DNA damage response and is overexpressed in most tumor types." (PMID 33352773, 2020). "We and others have previously shown that inhibition of poly (ADP) ribose polymerase-1 (PARP1), a member of the SSB base excision repair pathway, is a potent sensitizer of tumor cells to IR in HNSCC cells." (PMID 33133138, 2020). "PARP1 regulates the c-Jun N-terminal kinase (JNK) pathway, which is a driver of tumor development and treatment response." (PMID 32245040, 2020). "PARP1 expression in the normal tongue was significantly lower, 0.37 ± 0.45% of PARP-positive area over the total tissue area, when compared to tumor, 33.73 ± 8.84% of PARP-positive area over the total tissue area (P < 0.001)." (PMID 32636416, 2020). "We show high PARP1 and SLFN11 expression in DSRCT tumor material and antitumor effects following olaparib and TMZ combination treatment in a preclinical DSRCT model." (PMID 32279088, 2020). "Among the potential drug targets, we identified some well-known targets, including EGFR, ERBB2, and PARP1 as well as CDK2 and CDK4/6, which are related to the regulation of tumor cells development." (PMID 33287876, 2020). "miR-223 regulates several targets, such as NLRP3, NFIA, and PARP1, that are involved in the induction of apoptotic mechanisms observed in AYA-RMS tumor tissues." (PMID 31533233, 2019). "Consistent with the reduced olaparib‐induced PARP1 trapping in the presence of HMGA2, silencing HMGA2 was required to significantly reduce cell viability in our tumor cell models upon olaparib treatment in MMS exposed cells." (PMID 30289618, 2019). "We identified HMGA2 as a new interaction partner of PARP1, as a modulator of DNA damage‐induced PARP1 activity, and as an ADP‐ribose acceptor in human tumor cells." (PMID 30289618, 2019). "Since chemical inhibition of PARP1 through Olaparib also impairs BER, it significantly enhances TMZ-induced damage, exerting synergistic anti-tumor effects in GSCs lines." (PMID 31119097, 2019).
tumor (continued). "PICH knockdown had little effect on the apoptosis of luminal tumor cells, such as T47D and DFBC4–17, but exerted a pronounced effect on TNBC cells, exemplified by increased cleaved PARP1 and DNA fragmentation." (PMID 31160555, 2019). "Altogether, this study pinpoints DEK as an important mediator of the PARP1/2-dependent response of replicating cells to fork impairment, a previously unrecognized function of DEK which has implications for tumor therapy and warrants further investigation." (PMID 31408463, 2019). "First tested in vitro, thedrug selectively targeted tumor cells with BRCA1,BRCA2, or PTEN gene alterations with 20-to more than 200-fold greater potency than existing PARP1/2 inhibitors (such asolaparib, rucaparib, and veliparib) (Shenet al., 2013)." (PMID 31067289, 2019). "PARP1 mediates EBV replication during latency and LMP1 has been shown to alter expression of tumor-promoting genes by blocking histone methylation via PARP1 activation." (PMID 30931253, 2019). "Transcript levels of PARP1, PARP2 and PARP3 genes were evaluated in a panel of 17 RMS primary tumours (4 ARMSs and 13 ERMSs) by quantitative Real Time PCR (q-PCR) experiments." (PMID 30357520, 2019). "Since DLBCL is a tumor with high levels of DNA damage, targeting proteins involved in DDR and damage repair, such as WEE1 and PARP1, is a rational choice for therapy in DLBCL." (PMID 29489886, 2018). "Graft tumor samples were examined for apoptosis by assessing DNA fragmentation (TUNEL assay), caspase 3 processing and cleavage of the caspase-3 substrate PARP-1." (PMID 29755689, 2018). "The apoptotic cleavage fragments of PARP1 were only observed in A549 and HeLa cells, consistent with the preferable effect of CDDP on these tumours." (PMID 29449532, 2018). "Furthermore, it was determined that PARPi alters the activation status the endogenous inhibitor of E2F1 function, the retinoblastoma tumor suppressor (RB), wherein PARPi resulted in enrichment of hypophosphorylated (active) RB, suggesting that the functions of PARP‐1 suppression may be pleiotropic." (PMID 30467127, 2018). "While PARPi is in clinical development for PCa management, the clinical value of targeting PARP‐1 for the prevention of CRPC development, and progression in other tumor types, should be evaluated." (PMID 30467127, 2018). "In this regard, it is noteworthy that ki-67 intensity in tumours derived from HT-29 cells overexpressing CNTD2 is similar to control, whereas cleaved PARP1 increases." (PMID 30087414, 2018). "The suppression of tumor growth and the cell death induction in these hyperacetylated mice were accompanied by altered RAGE expression and PARP-1 cleavage as shown in whole-body IVIS images in the absence of fluorescent metastatic cells." (PMID 29880821, 2018). "Similar to our previous finding that hypoxia leads to increased sensitivity to PARP-1 inhibition in hypoxic tumour cells (due to decreased HRR), in this tumor model we observed an increased Caspase 3 expression in hypoxic regions after olaparib treatment." (PMID 29152107, 2017). "PARP1 protein is also highly expressed in IIB and IIIB stages of the tumor in comparison to IIA stage." (PMID 28993682, 2017). "At this condition, PARP1/2 in PBMC and tumor cells in the xenografts can be inhibited nearly totally and DSB accumulation progressively increases in tumor cells in the xenografts, which forms the basis of the in vivo anticancer activity of MPH." (PMID 27926532, 2017). "Drugs based on DNA repair mechanisms, such as poly (ADP-Ribose) polymerase 1 (PARP1) inhibitors, Chk inhibitors, and ATM/ATR inhibitors, play an important role in anti-tumor therapy." (PMID 29312562, 2017).